ZEB1 (zinc finger E-box binding homeobox 1)
Diseases named in the same sentence as ZEB1 in open-access papers (continued):
Sharing a sentence is not in itself a finding about the gene and the disease.
cancer (continued). "It turned out though, that in this specific cancer model, ZEB1 played a much more critical role and a knockout of ZEB1 did indeed interfere with metastasis." (PMID 41233338, 2025). "The remodeled HA matrix, orchestrated by ZEB1, facilitates the migration and invasion of cancer cells." (PMID 40178908, 2025). "Regarding ZEB1 regulation, studies in epithelial–mesenchymal transition and cancer stemness models indicate that H3K18la and H3K9la enrichment at ZEB1 regulatory elements correlates with transcriptional activation." (PMID 41583433, 2025). "The significance of ZEB1 as a driving force in tumorigenesis across different cancer types, including HCC and CCA, has been extensively reported." (PMID 40830586, 2025). "EMT, which plays an important role in cancer cell chemoresistance, is a complex process controlled by various transcriptional regulators such as Twist1, Snail, Slug and Zeb1." (PMID 40344465, 2025). "Since ZEB1 is also involved in radioresistance in different cancers, we analysed the role of ETV1 in this process." (PMID 40275610, 2025). "In conclusion, ZEB1 orchestrates cancer cell migration and invasion through comprehensive regulation of the HA network, including ITIH2." (PMID 40178908, 2025). "It was previously demonstrated that ZEB1 suppresses the transcriptional expression of epithelial genes, including E-cadherin, in cancer." (PMID 40918458, 2025). "It was also reported that Zinc finger E-box binding homeobox 1 (ZEB1) participates in cancer progression and metastasis." (PMID 40535133, 2025). "We show that higher ZEB1 activation correlates with higher mitochondrial fission as marked with Drp1 upregulation, both in cell models and subset of patient cancer tissue samples." (PMID 40830586, 2025). "Experiments showed that Daxx shows the cancer inhibitory effect by interacting with ZEB1 and directly inhibiting the activity of the E‐cadherin promoter in a ZEB1‐dependent manner." (PMID 40130316, 2025). "The cancer cell metastasis is mediated by hypoxia-inducible factor 1α (HIF1α)/zinc finger E-box binding homeobox 1 (ZEB1) axis, which is involved in the process of epithelial–mesenchymal transition (EMT)." (PMID 40863244, 2025). "Kahlert and colleagues reported that activation of the Wnt/β‐catenin pathway caused the upregulation of Zeb1, an EMT‐activating transcription factor that is one of the most important components of classical EMT‐related cancer biology in GB cells." (PMID 40400263, 2025). "EMT-TFs are activated by diverse TME signals, and their upregulation (e.g., ZEB1, SNAIL, and TWIST) is associated with a shift toward a stem-like phenotype in cancer cells." (PMID 40361472, 2025). "Overall, these findings indicate that the suppression of CDS1 expression in mesenchymal-like cancers by ZEB1 results in their strong dependency on CDS2." (PMID 40615674, 2025). "Tissue/EV miR-200 low/ZEB1 high EMT axis correlates with adverse survival across multiple cancers, as supported by meta-analysis and NSCLC cohort data." (PMID 41462674, 2025). "The unexpected role of ZEB1 established by our study offers additional approaches for future cancer immunotherapy." (PMID 38183060, 2024). "ZEB1 induces EMT during cancer metastasis by transcriptionally repressing CDH1, which encodes E-cadherin." (PMID 39518976, 2024). "Anti-cancer agents such as Eriodictyol have been used to reduce ZEB1 expression to suppress EMT in glioblastoma." (PMID 38733529, 2024). "A transcription factor called ZEB1 participates in the EMT, which is linked to enhanced cancer aggressiveness and treatment resistance." (PMID 38511067, 2024). "Further investigations are warranted to elucidate the relationship between CD73 and ZEB1, with the potential for targeting them as therapeutic alternatives for cancer treatment in the near future." (PMID 38388432, 2024).
cancer (continued). "Zinc finger E‐box binding homeobox 1 (ZEB1) has been identified as a key factor in cancer cell differentiation and metastasis, and has been well studied in the field of cancer cell biology." (PMID 39362647, 2024). "Several DUBs, including USP10, USP18, USP22, USP43, and USP51 have been identified as key regulators of ZEB1 stability, thereby promoting proliferation, migration and invasion of cancer cells across different malignancies." (PMID 39736693, 2024). "Induction of PI3K/Akt signaling by BAG4 leads to an increase in cancer metastasis via ZEB1 overexpression." (PMID 38733529, 2024). "Pharmacological inhibition of selected lipogenic enzymes (SCD and FADS2) allows the manipulation of ferroptosis sensitivity preferentially in high-Zeb1-expressing cancer cells." (PMID 39009641, 2024). "miR‐200a has been reported to be down‐regulated in cancer and functions as a cancer suppressor via suppressing ZEB1/2 transcription factors to inhibit the EMT." (PMID 38299307, 2024). "These miRs play a crucial role in regulating the epithelial-mesenchymal transition in different types of cancer by repressing the transcription factors ZEB1 and ZEB2 in a bidirectional manner." (PMID 39001526, 2024). "Overexpression of ZEB1 in OC cells promotes cancer cell-TAM spheroid formation in vitro and in mice." (PMID 39513610, 2024). "Previous studies have indicated that LAMC2 regulates the TGF-β signaling pathway and the integrin β1- and ZEB1-dependent pathways to promote cancer progression." (PMID 39223142, 2024). "We here show that various forms of EMT activation, including TGFβ stimulation and acquired therapy resistance, increase ferroptosis susceptibility in cancer cells, which depends on the EMT transcription factor Zeb1." (PMID 39009641, 2024). "Classical EMT transcription factors like Snail, Slug, Twist, and ZEB1/2 are upregulated in cancer cells, which enhances their invasive and metastatic potential." (PMID 39409891, 2024). "Simultaneously, it engages in auto-amplification of this gene expression network within the cell, thus maintaining a cancer stem-like status through positive feedback mediated by ZEB1." (PMID 39420119, 2024). "High levels of ZEB1 drive the progression of certain cancers, including ovarian, breast, pancreatic, liver, and lung cancers." (PMID 39065699, 2024). "This study is dedicated to investigating the impact of CD73 on ZEB1, aiming to elucidate the intricate connections between them and understand their implications in the progression of cancer." (PMID 38388432, 2024). "Accumulating evidence has shown that transcription factor ZEB1 is widely overexpressed in cancers, including GC." (PMID 38965605, 2024). "Many studies demonstrate that inhibiting the ZEB1 expression can suppress the cancer progression, including BC." (PMID 38481182, 2024). "As previous reports have suggested that miR200c reduces EMT in cancer cells through the regulation of ZEB-1, we aimed to investigate the role of miR200c in modulating the sensitivity of organoids to EGFR-TKIs." (PMID 39766891, 2024). "The expression of TGF-β interacts with both the Snail and ZEB1 proteins to influence cancer–TME crosstalk related to immune evasion." (PMID 38672562, 2024). "Circ-ACAP2 sponges miR-21-5p to suppress STAT3 signaling in cancers, lowering ZEB1 expression and impairing EMT." (PMID 38733529, 2024). "In EMT cancer cells, ZEB1 is high, and it transcriptionally represses miR-200 expression, resulting in increased PD-L1 and enhanced EMT and metastasis." (PMID 38893094, 2024). "The zinc-finger E-box binding proteins 1 and 2 (ZEB1 and ZEB2) have been associated with malignancy in several types of cancer." (PMID 38473317, 2024). "Our study confirms this findings, demonstrating that the regulation of ZEB1 by DUBs constitutes a general mechanism driving cancer cells aggressiveness, which extends to hematological malignancies capable of acquiring EMT-like marker features, such as MM." (PMID 39736693, 2024).
cancer (continued). "To further test the effects of combination drugs (ZEB1 activator and Rosiglitazone) on inducing a cancer to adipose transition, we performed bioinformatics analysis to the RNA‐seq data from our experiments." (PMID 39258786, 2024). "MALAT-1 contributes to medication resistance and cancer aggressiveness by functioning as a miR-200a sponge and encouraging ZEB1 expression." (PMID 38511067, 2024). "Our data are of potential translational relevance and suggest a combination of ferroptosis activators and SCD inhibitors for the treatment of aggressive cancers expressing high Zeb1." (PMID 39009641, 2024). "Zeb1-binding regions were associated with an active, open (FADS2) or inactive, closed (SCD and FASN) chromatin state in Zeb1high-expressing cancer cells, and an inverse pattern in Zeb1-depleted cells." (PMID 39009641, 2024). "ZEB1 is an EndMT‐inducing transcription factor involved in cancer cell metastasis through the Akt‐MAPK and Wnt pathways." (PMID 38778448, 2024). "Due to their central role in EMT and extensive studies in cancer, ZEB1, ZEB2, SNAI1, SNAI2 and TWIST1 are considered as the core EMT-TFs." (PMID 39164745, 2024). "Our study not only identified a hub biomarker related to CRC prognosis but also revealed the specific molecular mechanisms through which ZEB1 affects cancer progression." (PMID 39193340, 2024). "Studies have demonstrated that PN secreted by stromal cells of various cancer can also modulate the expression of EMT-associated proteins such as β-cat, E-cad, and Zeb-1, supporting cancer metastasis." (PMID 38935747, 2024). "ZEB1 is a critical inducer of EMT in cancer, and the interaction between ZEB1 and EMT can lead to drug resistance." (PMID 38184689, 2024). "One of the ZCCHC24 targets, ZEB1, is a transcription factor that promotes the expression of cancer stemness genes and reciprocally induces ZCCHC24 expression." (PMID 39420119, 2024). "In vitro experiments using human PCa sections and in vitro cultures found that LA and EPA exert anti-cancer effects by regulating Ca2+ entry, which is involved in Zeb1 regulation and cancer cell migration." (PMID 38164282, 2024). "The current study findings have potential clinical implications: ZEB1-expressing cancer cells demonstrate high resistance to therapy but sensitivity to ferroptosis-inducing drugs." (PMID 39256881, 2024). "Our data are of potential translational relevance and suggest a combination of SCD inhibitors and ferroptosis activators for the treatment of aggressive cancers expressing high Zeb1." (PMID 39009641, 2024). "miR-200b maps to the long arm of chromosome 1q36.33 and has been implicated in several types of cancer and specifically targets transcription factors that promote EMT, such as zinc-finger E-box-binding homeobox 1 (ZEB1)." (PMID 39343796, 2024). "Consistent with previous studies that an EMT-TF Zeb1 controls the stemness of neural stem cells as well as cancer initiating cells, Zeb1 expression was found in many Sox2+ neural stem/progenitors in the VZ of DG at E14 (Figures 2A1–A8)." (PMID 39268037, 2024). "For the experimental validation, we chose aggressive cell lines from liver (Hep3B, Huh‐7), breast (MDA‐MB‐231), and colorectal (SW480, SW620) cancers to create ZEB1 overexpression models." (PMID 39258786, 2024). "This is also reflected by the correlation (ELOVL5, FADS2 and ACSL4) and anti-correlation (FASN and SCD) of these enzymes with Zeb1 expression in cancer cell lines." (PMID 39009641, 2024). "For Zeb-1, only stromal expression was correlated with N stage (p = 0.025), and cancer stage (p = 0.009)." (PMID 38935747, 2024). "These investigations should soon clarify the correlation between ZEB1/2‐expressing cells and cancer immunity in HNSCC." (PMID 39362647, 2024). "Recently, ZEB1 has been indicated as a factor that induces cancer proliferation and drug resistance favouring the growth and viability of cancer cells." (PMID 38773406, 2024).
cancer (continued). "Previous studies have proposed an indirect crosstalk molecular mechanism among EMT, miR-200, ZEB1, PD-L1, and metastasis in cancer cells." (PMID 38893094, 2024). "As the crucial role of EMT in the migration and invasion of epithelial cell‐derived malignant tumors, we examined the expression of mesenchymal markers (N‐cadherin, ZEB1, Vimentin, Snail) and epithelial marker (E‐cadherin)." (PMID 38733179, 2024). "ZEB1 is a key factor for cell fate determination, including cell plasticity and cancer cell metastasis." (PMID 38578740, 2024). "A number of bioinformatic analyses have shown that many cancer cells express ZEB1/2 proteins simultaneously, while several normal cell types do not." (PMID 39362647, 2024). "Zeb1, downstream of pSmad3, contributes to maintaining the stemness of cancer-initiating cells (CICs) by inhibiting cellular senescence." (PMID 39268037, 2024). "ZEB1 is considered an oncoprotein because it is highly expressed in many malignant tumors derived from epithelial tissues." (PMID 38822380, 2024). "KEGG pathway enrichment was performed on 74 target genes using DAVID, and four genes, BMPR2, HMOX1, HNRNPK and ZEB1, were enriched on the “microRNAs in cancer” signal pathway." (PMID 38693503, 2024). "Zinc finger E-box binding homeobox 1 (ZEB1) transcription factor is frequently expressed in carcinomas, being involved in normal development and disease by TGFβ-induced responses and EMT." (PMID 39275004, 2024). "Although initially described as a transcriptional repressor, our data confirm previous ChIP-seq analyses in carcinoma models showing the capacity of ZEB1 to mediate both transcriptional activation and repression in similar proportions." (PMID 38519642, 2024). "To analyze the lineage specificity of ZEB1 binding compared to carcinoma models, we performed a comparative analysis with a previously published ZEB1 ChIP-seq dataset performed in the MDA-MB-231 breast cancer cell line." (PMID 38519642, 2024). "Together, these results demonstrate that ZEB1/YAP1 axis in cancer cells potentially functions downstream of ITGA5/ITGB1 interaction with fibronectin on the surface of fibroblasts." (PMID 36936987, 2023). "We did, however, not observe ZEB1 associated to the tubulin spindle apparatus as noted in cancer cell lines, but we did notice a few scattered CMs with cytoplasmic ZEB1." (PMID 36862248, 2023). "The transcription factor ZEB1 enables and maintains cell plasticity in cancer cells and is best known for inducing an epithelial-to-mesenchymal transition (EMT) during embryonic development and cancer progression (reviewed in23–26)." (PMID 37978290, 2023). "ZEB1 is involved in cell differentiation and transformation in development and pathogenesis of many diseases including cancer and tissue fibrosis." (PMID 37081200, 2023). "Whereas SNAI1 was equally expressed or slightly downregulated in the partial-EMT subgroups of basal-like cancers, ZEB1, ZEB2, and TWIST1 were more highly expressed in cluster 1 that is defined by the EMT-up genes." (PMID 38111531, 2023). "Here, we found that ZEB1, a regulator of cell plasticity in cancer stem cells, exhibits contrasting roles in inflammation and immunosuppression." (PMID 37978290, 2023). "Functionally, knocking down Zeb1 in LINC00963 overexpressed cancer cells was sufficient to abolish EMT and cell mobility, demonstrating its importance in LINC00963-induced metastatic phenotypes." (PMID 36604626, 2023). "EMT-related transcription factors include the Snail family (Snail, Slug, etc.), ZEB family (ZEB1, ZEB2), and Twist, and although they vary depending on the type of cancer, Snail, ZEB1, and Twist are expressed by strengthened TGF-β/SMAD signal stimulation." (PMID 38201481, 2023). "Zinc finger E-box-binding homeobox 1 (ZEB1) is involved in epithelial-to-mesenchymal transition (EMT) and is significantly associated with poorer cancer prognosis, including for HCC." (PMID 37373948, 2023).
cancer (continued). "Insulin-like growth factor-binding protein 2, which is significantly upregulated in SACC, plays a crucial role in the invasion and metastasis of this cancer type by modulating the NF-κB/ZEB1 signaling pathway." (PMID 37296849, 2023). "By utilizing the new construct, we studied the role of Zn2+-binding by ZEB1 in the cellular behaviors of TNBCs in vitro in the context of cancer metastatic outgrowth." (PMID 36910659, 2023). "In HCC, SNHG6 upregulates ZEB1 expression by binding miR-101-3p and, in combination with downregulation of Smad7, induces epithelial–mesenchymal transition, speeding up cancer-cell metastasis." (PMID 40636922, 2023). "For example, multiple studies have reported that EMT drivers, such as SNAI2, ZEB1 and Twist1, play critical roles in cancer cell stemness in cancers." (PMID 36808651, 2023). "We also observed differential expression of cancer-metastasis-inducing genes, such as ZEB1, MMP9, CLDN3, TWIST1 and N-cadherin, between LVI(+) and LVI(−) samples in some patients, indicating a correlation of VCAN with EMT genes in LVI(+) samples." (PMID 37108649, 2023). "For example, ZEB1 repression via class I HDAC inhibition can resensitize some cancer cells to chemotherapy." (PMID 37761927, 2023). "ZEB1 is a well-characterized transcription factor known to play a role in the regulation of epithelial–mesenchymal transition (EMT) in cancer." (PMID 37444395, 2023). "The transcription factor ZEB1 is best known for promoting cellular plasticity in epithelial cells during cancer initiation and progression." (PMID 37978290, 2023). "In GBM, FGFR1 is known to regulate cancer stemness and therapy resistance through the transcription factor ZEB1, which is also regulating GBM invasion." (PMID 37579831, 2023). "The RAE1 gene specifically has been shown to induce aggressive cancer phenotypes by mediating EMT via ZEB1 expression." (PMID 36835368, 2023). "There were various cancer-related genes involved in TGFβ signaling such as ZEB1, Snail1 and Vimentin that played vital roles in the malignant progression of PC." (PMID 37322017, 2023). "Among 610 cancer cell lines, those with high ZEB-1 transcription levels were remarkably more sensitive to a GPX4 inhibitor." (PMID 37046995, 2023). "Further analysis to determine molecular insights of how Zeb1 is negatively regulated by APJ in cancer is required." (PMID 36776217, 2023). "Healthy gastric, colon, esophageal, and pancreatic tissues had R coefficients between VIP and ZEB1, an expression similar to those seen in TCGA cancer tissues (p < 0.0001 for all analyses)." (PMID 37444395, 2023). "In this respect, there is ample evidence to demonstrate that Zeb1 confers characteristics of ‘stemness’, including self-renewal, and increases invasiveness in cancer." (PMID 37759786, 2023). "In cancer cells, ZEB1 is not only activated by most signaling pathways, but its expression is also essential for enabling the complete functionality of these pathways." (PMID 38097578, 2023). "In the process of EMT transformation, up-regulated expression of transcription factors, such as Snail1, Twist1, Zeb1, and Zeb2, can increase the migration and invasion of cancer cells." (PMID 37115802, 2023). "The transcription factor ZEB1 is best known for triggering an epithelial-to-mesenchymal transition (EMT) in cancer cells." (PMID 38097578, 2023). "ZEB1 (Zinc finger E-box-binding homeobox 1) has been known to trigger the EMT process in human cancer types." (PMID 38152652, 2023). "Mathematical modeling suggests that this mixed/hybrid E/M state and, hence, cancer cell plasticity is chiefly regulated by the “miRNA-200c-3p-ZEB1” reciprocal feedback loop." (PMID 38139138, 2023). "The activation of EMT-TFs, such as Snail, Twist, and Zeb1, gives cancer cells the ability to invade and migrate." (PMID 37573347, 2023). "In recent years, ZEB1 has emerged as a key regulator of cell plasticity that plays important functions in non-cancer cells." (PMID 38097578, 2023).